RNU6-1275P (RNA, U6 small nuclear 1275, pseudogene)
Gene: Small nuclear RNA gene on chromosome 2 (147,877,422 to 147,877,528, forward strand). Ensembl gene ENSG00000212389.
Homologues: Orthologues: chimpanzee U6 (100% identical), macaque U6 (77% identical), pig U6 (74% identical), rat LOC120095714 (69% identical), mouse Gm24164 (65% identical), mouse Gm54984 (65% identical), dog U6 (63% identical), pig U6 (56% identical), guinea pig U6 (54% identical), pig U6 (53% identical). Paralogues in human: RNU6-1209P (81% identical), RNU6-797P (81% identical), RNU6-242P (80% identical), RNU6-1083P (79% identical), RNU6-1287P (79% identical), RNU6-1094P (79% identical), RNU6-1322P (79% identical), RNU6-992P (79% identical), RNU6-1022P (78% identical), RNU6-1031P (78% identical), RNU6-1047P (78% identical), RNU6-1091P (78% identical), and 1287 more.